JUND (JunD proto-oncogene, AP-1 transcription factor subunit)
Description:
Transcription factor binding AP-1 sites. Heterodimerizes with proteins of the FOS family to form an AP-1 transcription factor complex, thereby enhancing their DNA binding activity to an AP-1 consensus sequence 3'-TGA[GC]TCA-5' and enhancing their transcriptional activity.
Synonyms: AP-1
Tractability: Small molecule: a structure with a bound ligand is known. PROTAC: ubiquitination databases record sites on it; its protein half-life has been measured.
Target class: Transcription factor
Gene: Protein-coding gene on chromosome 19 (18,279,694 to 18,281,622, reverse strand). Ensembl gene ENSG00000130522.
Subcellular location: Nucleus
Subcellular location (Human Protein Atlas): Nucleoplasm
Pathways (Reactome):
Signal Transduction: Estrogen-dependent gene expression; NGF-stimulated transcription
Immune System: Regulation of PD-L1(CD274) transcription
Gene Ontology:
Molecular function: enzyme binding; protein binding; sequence-specific double-stranded DNA binding; transcription cis-regulatory region binding; DNA-binding transcription factor activity, RNA polymerase II-specific; RNA polymerase II cis-regulatory region sequence-specific DNA binding; DNA binding; DNA-binding transcription activator activity, RNA polymerase II-specific; DNA-binding transcription factor activity; double-stranded DNA binding; nuclear receptor binding; sequence-specific DNA binding; transcription coregulator binding
Biological process: negative regulation of transcription by RNA polymerase II; positive regulation of transcription by RNA polymerase II; regulation of cell cycle; regulation of cell population proliferation; regulation of transcription by RNA polymerase II; response to steroid hormone; cellular response to fatty acid; cellular response to hypoxia; cellular response to polyamine macromolecule; circadian rhythm; epithelial cell proliferation; negative regulation of cardiac muscle hypertrophy; negative regulation of epithelial cell proliferation; positive regulation of macrophage activation; positive regulation of peroxisome proliferator activated receptor signaling pathway; regulation of DNA-templated transcription; response to cold; response to forskolin; response to light stimulus; response to lipopolysaccharide; response to mechanical stimulus; response to mercury ion; response to peptide hormone; response to water deprivation; transcription by RNA polymerase II
Cellular component: nucleoplasm; RNA polymerase II transcription regulator complex; transcription factor AP-1 complex; transcription repressor complex; chromatin; nucleus; transcription regulator complex; protein-containing complex; protein-DNA complex
Genetic constraint (gnomAD): Loss-of-function variants: 2 observed, 6.94 expected, observed/expected ratio (o/e) 0.29, 90% interval 0.12 to 0.91. That is too few expected variants to judge how well the gene tolerates losing a copy. Missense variants: 479 observed, 382.89 expected, observed/expected ratio (o/e) 1.25, 90% interval 1.16 to 1.35. Synonymous variants: 335 observed, 212.06 expected, observed/expected ratio (o/e) 1.58, 90% interval 1.44 to 1.73.
Homologues: Orthologues: chimpanzee JUND (99% identical), macaque JUND (98% identical), dog JUND (94% identical), guinea pig JUND (87% identical), mouse Jund (81% identical), rat Jund (81% identical), zebrafish jund (54% identical), Drosophila melanogaster Jra (29% identical), Caenorhabditis elegans F19B2.6 (23% identical). Paralogues in human: JUN (49% identical), JUNB (41% identical).
Diseases named in the same sentence as JUND in open-access papers:
JUND is named in the same sentence as 97 diseases in open-access papers, as found by Europe PMC text mining. Sharing a sentence is not in itself a finding about the gene and the disease. The quoted sentences say what the papers report.
breast cancer (20 papers, 2005 to 2025). A primary or metastatic malignant neoplasm involving the breast. "CD99SF engagement by antibodies in breast cancer increased the expression of JunD and FosB AP-1 factors, along with the activation of PI3K-Akt signaling pathway by phosphorylation of Src, Akt, p38 MAPK, ERK and JNK." (PMID 38804310, 2024). "miR-548d-3p directly targets JunD and loss of miR-548d-3p enhances JunD/RSK3 signaling in the chemotherapy resistant of breast cancer." (PMID 34512545, 2021). "This was confirmed by testing THC in breast cancer cells with silenced JunD and JunD knockout mice-derived fibroblasts, where the anti-proliferative effects of THC were significantly reduced." (PMID 32708138, 2020). "Mechanistically, THC’s anti-cancer effects in breast cancer can be mediated by modification of JunD, a transcription factor." (PMID 32708138, 2020). "KRT5 combines with transforming growth factor beta receptor 3 (TGFBR3) and transcription factor JunD to promote breast cancer cell growth." (PMID 29069744, 2017). "Anandamide inhibits adenylyl cyclase (AC) and thus activating the Raf-1/ERK/MAP pathway in ER+/PR+ breast cancer cells whilst THC activates the transcription factor JunD to finally execute action towards apoptosis in ER−/PR+ breast cancer cells." (PMID 25115386, 2014). "We also report that a highly specific AHR agonist significantly (P < 0.05) inhibits the expression of E2F1, CCND1 (known as Cyclin D1), MYB, SRC, JAK2, and JUND in breast cancer cells." (PMID 24171117, 2013). "The expression of the Jun proteins c-Jun, JunB and JunD as well as the Fos family members c-Fos, FosB, Fra-1 and Fra-2 in the analysed mammary tumour tissues was described in our prior publication." (PMID 15928662, 2005). "Finally, we examined the relationship between JNK pathway genes and JUN/JUND expression in primary ER+ breast cancers from the TCGA (n = 812)." (PMID 40826108, 2025). "Previous studies have demonstrated that these transcription factors play critical roles in various cancers; for example, HINFP shows significant regulatory effects in bladder cancer, POU2F2 is linked to lung cancer, and JUND and FOXC1 are key in colorectal and breast cancer, respectively." (PMID 40417238, 2025). "Meanwhile ALPP, JUND, ZBTB7A in gastric cancer, prostate cancer, breast cancer 33-35 and other cancers promote the progress of cancer." (PMID 32626531, 2020). "This trend was also consistent across a number of cancers: in particular, highly rewired TFs such as BHLHE40, JUND, and MYC behaved similarly in lung, liver, and breast cancers." (PMID 32728046, 2020). "Accordingly, we detected the mRNA and protein expression status of JunD and RSK3 in a panel of breast cancer cell lines." (PMID 31937753, 2020). "Ectopic expression of FOXD3 stimulated the expression of miR-548d-3p and repressed JUND and RPS6KA2 mRNA expression, as well as greatly enhancing the BET sensitivity of luminal breast cancer cells." (PMID 31937753, 2020). "Consistently, JunD and RSK3 both had much higher mRNA and protein levels in luminal and HER2+ breast cancer cell lines (MCF7, BT474 and MDA-MB-453) compared with BLBC cells (SUM1315, MDA-MB-231, BT549 and MDA-MB-157)." (PMID 31937753, 2020). "Tightly positive correlations of mRNA levels between JUND and RPS6KA2 were observed in different subtypes of breast cancer." (PMID 31937753, 2020). "Lastly, to further confirm the role of JunD/RSK3 signalling in BET resistance, RPS6KA2 and JUND were respectively knocked down in two JQ1-resistant breast cancer cell lines (BT474 and MDA-MB-453), and showed that the silencing of both RPS6KA2 and JUND restored the JQ1 sensitivity of these cells." (PMID 31937753, 2020).
lung carcinoma (16 papers, 2013 to 2025). "Our data indicated that patients with higher expression of DDX3X/CBS, DDX3X/METTL16 and DDX3X/JUND exhibited poorer overall survival and progression-free interval, suggesting the prognostic value of DDX3X and its associated genes for lung cancer patients." (PMID 40885716, 2025). "In particular, JUND has been identified as a crucial factor in Ras-driven lung cancer, suggesting a significant role in oncogenesis." (PMID 41323280, 2025). "Treatment with CUR also reduced activation of HLJ1 via activation of the JNK/JunD pathway and also led to increased expression of E‐cadherin in lung cancer cells." (PMID 37697969, 2023). "Inhibition of KDM4C with shRNAs or SD70 treatment reduced the basal expression levels of TGF-β2, BMP2 and JUND while increasing the expression level of GDF11 in lung cancer cells." (PMID 33558705, 2021). "Finally, by performing co-immunoprecipitation and immunofluorescence assay, we excluded the possibility of direct interaction between DDX3X and JUND in lung cancer cells." (PMID 40885716, 2025). "Given that JUND is a transcription factor in lung cancer progression, we further investigated whether JUND acts as a nexus between METTL16 and DDX3X." (PMID 40885716, 2025). "Thus, to confirm a function of JunD in lung cancer cells, JunD protein expression was knocked out via CRISPR/Cas9 in primary lung KP cells." (PMID 34236045, 2021). "In addition, miR-663a regulated cell cycle and invasion by targeting AP-1 component JunD, which provides new insights into the molecular mechanisms of lung cancer progression." (PMID 27184257, 2016). "Lastly, we uncovered that DDX3X controls METTL16 transcription through a direct interaction with JUND transcripts, thus delineating an intact pathway elucidating how DDX3X regulates lung cancer progression." (PMID 40885716, 2025). "To validate the involvement of JUN family TFs in TGF-β-induced EMT of lung cancer cells, we first examined the changes in expression of JUN, JUNB, and JUND by TGF-β treatment." (PMID 36183833, 2022). "A number of established lung cancer oncogenes have also been included in the classifier, such as IL1R2, JUNB, EGFR, SOX9, FOSB, and JUND." (PMID 27935865, 2017). "Using siRNA knockdown, we confirmed that JunD downregulation decreased expression of cyclin D1, cyclin E and MMP9 in lung cancer cells." (PMID 27184257, 2016). "Quantitative RT–PCR (QRT–PCR) revealed that the expressions of JUN and JUNB but not of JUND mRNA were increased by TGF-β in A549 and LC2/ad lung cancer cell lines." (PMID 36183833, 2022). "This work identifies JunD, not c-Jun, as the crucial substrate of JNK signaling and oncogene required for Ras-induced lung cancer." (PMID 34236045, 2021).
prostate carcinoma (12 papers, 2014 to 2025). A carcinoma that arises from epithelial cells of the prostate gland. "JunD and β-catenin have previously been found to play an oncogenic role in prostate cancer, indicating that menin can increase the tumorigenic potential of AR-negative prostate cancers by increasing the activation of JunD and β-catenin." (PMID 39336822, 2024). "JunD is a crucial regulator for prostate cancer cell proliferation and a latent therapeutic target for PCa." (PMID 37049787, 2023). "More intriguingly, treatment with MI503 greatly inhibited the growth of prostate cancer cells and reduced the expression of menin and JunD expression in DU145 and PC3 cells." (PMID 37049787, 2023). "Meanwhile, JUND contributes to escape from programmed cell death and confer radio-resistance of prostate cancer (PCa) cells." (PMID 32318351, 2020). "On the other hand, Fra-1, Fra-2 and JunD were shown to contribute to prostate cancer growth and survival after radiation." (PMID 28684765, 2017). "We also showed that GADD45α and γ induce cell cycle arrest and apoptosis in prostate cancer cells, and NF-κB- as well as JunD-mediated repression of GADD45α and γ are essential for prostate cancer cells to escape cell death." (PMID 26885618, 2016). "Interestingly, AR/p52-02 was also previously found to inhibit the interaction between AR and JunD in our study on an ROS generation pathway in prostate cancer cells." (PMID 26622945, 2015). "Menin may also promote AR-positive prostate cancer growth by promoting JunD and TMPRSS2 expression." (PMID 39336822, 2024). "Indeed, JunD increases prostate cancer cell migration in an ERK-dependent manner." (PMID 34236045, 2021).
colon carcinoma (7 papers, 2012 to 2025). "An integrative study of colon cancer invasiveness identified transcriptional reprogramming events mediated by transcription factors like JunD that drive metastatic behavior." (PMID 41614813, 2025). "Disrupting the expression of one of the highly ranked transcription factors JunD, an AP-1 complex protein, confirms functional relevance to colon cancer cell migration and invasion." (PMID 33413550, 2021). "MALAT1 is also increased in colon cancer cells, directly binding to miR-663a, thus acting as a competing endogenous lncRNA; as a result, important cancer-related miR-663a targets (TGFB1, PIK3CD, P21, JunB, and JunD) were affected." (PMID 32183400, 2020). "We then explored the mechanism by which PES1 expression is controlled in human colon cancers and demonstrated that c-Jun, but not JunB, JunD, c-Fos, or mutant c-Jun, positively regulated PES1 promoter transcription activity." (PMID 22860098, 2012).
melanoma (7 papers, 2010 to 2025). A malignant, usually aggressive tumor composed of atypical, neoplastic melanocytes. "Besides ETS1, we predicted AR, E2F1 and JUND as the most significant regulators in melanoma patients with a TERT promoter mutation." (PMID 31888467, 2019). "Notably, both JUNB and JUND are downregulated in invasive/late (stage 4) melanoma compared to stage 1 melanoma, and several DE genes from stage 1 vs. stage 4 comparison enriched in MAP kinase and Ras GTP binding processes." (PMID 32079144, 2020). "Module M3 contained JUND, SOX2, THAP11, and JUN, as well as regulators for C5 Melanoma MAGEA4, C6 Melanoma GJB2, C2 melanoma EDNRB, and C1 melanoma CDH19." (PMID 37435067, 2023). "For the level of mRNA expression in the TCGA database and melanoma cell lines, SLC39A14, PSMB4, CRELD2, CDKN2A and TIMP1 were higher in SKCM tissues than in normal skin tissues, and NDRG1, ATF3, and JUND had an opposite trend." (PMID 36226170, 2022). "By contrast, inhibition of ATF2 repressed tumorigenesis of melanoma via increasing JNK/Jun and JunD activities." (PMID 27377902, 2016). "In melanoma, the deubiquitinase ubiquitin-specific protease 7 (USP7) indirectly enhances FSP1 expression and ferroptosis resistance through stabilization of the transcription factor Jun D proto-oncogene (JunD)." (PMID 40862825, 2025).
diabetes (4 papers, 2021 to 2024). "We have recently reported that JunD downregulation in cardiomyocytes alters the balance between oxidant and antioxidant enzymes leading to oxidative stress, inflammation, and myocardial dysfunction in experimental and human diabetes." (PMID 38580969, 2024). "Also, SGLT-2i can prevent early myocardial injury in diabetes and mitigate the progression to HF by modulating the JunD/PPAR-γ pathway." (PMID 37805494, 2023). "Unlike other commonly used drugs such as metformin or GLP‐1, which acutely improve glucose control in diabetes, MI treatment epigenetically regulates the menin/JunD/Pbk axis, therefore taking a relatively longer time to increase beta cell mass and improve glucose control in diabetes." (PMID 33821572, 2021). "Use of MI to block the interaction between menin and JunD induces Pbk expression, increases beta cell proliferation, and ameliorates HFD‐induced diabetes." (PMID 33821572, 2021).
glioma (4 papers, 2014 to 2024). A benign or malignant brain and spinal cord tumor that arises from glial cells (astrocytes, oligodendrocytes, ependymal cells). "Protein levels of both ZNF350 and JUND were upregulated in HECW1-deficient glioma cells." (PMID 38049396, 2023). "Similarly, R322H and E408Q isolated from a sporadic glioma and non-small cell lung cancer patient, respectively, did not affect MLL1/MLL2 or JunD complexes, which suggest that these effects are either minimal or passenger rather than driver mutations for these pathologies." (PMID 35941657, 2022).
B cell lymphoma (3 papers, 2024 to 2025). "ChIP-seq data from the CH12 mouse B cell lymphoma line indicates that both c-Jun and JunD can bind at the +49 kb DAR site that gains accessibility." (PMID 39149372, 2024). "The results of the Western blot analysis comparing normal lymph nodes to B cell lymphoma nodes indicated that STAT1 and JUND are significantly overexpressed in lymphomas." (PMID 39518046, 2024).
hepatocellular carcinoma (3 papers, 2015 to 2020). A malignant tumor that arises from hepatocytes. "Additionally, miR663a’s downregulation fostered cell proliferation by JunD overexpression in small-cell lung carcinoma, and HMGA2 in hepatocellular carcinoma, while Transforming Growth Factor-1 (TGF-β1) overexpression was linked with invasion in the tumour type." (PMID 32102337, 2020).
leukaemia (3 papers, 2015 to 2020). "In the leukemia cell line K562, LTR5_Hs elements are enriched for binding of multiple TFs that control cell cycle and proliferation (e.g., cMYC, MAX, JUND, PU1, and P300), which might reflect the transformed phenotype of these cells." (PMID 33202765, 2020).
liver fibrosis (3 papers, 2012 to 2018). "Among the enriched TFs of dark genes in the most-DILI group, we detected, for instance, E2F1, which has been demonstrated to be involved in liver fibrosis, a common end-point of compound-induced liver injury, as well as JUND in the inflammatory process in liver." (PMID 30515189, 2018). "JUND and CEBP are involved in the regulation of the transcriptional activity of hepatic stellate cells, thereby promoting liver fibrosis." (PMID 28206970, 2017).
myeloma (3 papers, 2012 to 2024). "The gene JUND has been shown to modulate the development of drug resistance in a majority of patients on Bortezomib-based anti-myeloma therapy; three of the miRNAs identified in the original study as regulators of JUND were predicted using our MD model." (PMID 22253745, 2012).
non-small cell lung carcinoma (3 papers, 2016 to 2022). A group of at least three distinct histological types of lung cancer, including non-small cell squamous cell carcinoma, adenocarcinoma, and large cell carcinoma. "JUND accelerates tumor cell growth, inhibits apoptosis and enhances invasion in non-small cell lung cancer." (PMID 32318351, 2020).
Obesity (3 papers, 2019 to 2022). Accumulation of substantial excess body fat. "Studies on obese mice models have identified JUND as a key metabolic regulator of lipid metabolism and obesity-induced cardiomyopathy." (PMID 36232337, 2022). "Another study showed that miR-494-3p targets JunD and miR-494-3p/JunD is a novel molecular axis involved in obesity-related metabolic cardiomyopathy." (PMID 34409072, 2021).
pancreatic cancer (3 papers, 2021 to 2023). "JUND was also reported to regulate the progression of pancreatic cancer by activating the tumor suppressor gene RASSF10." (PMID 34290570, 2021). "In KC, KC;iASPPΔ8/Δ8, and KPC tissues, JunB, JunD and nuclear p-p65RelA are not expressed in morphologically normal acini but are readily detectable in metaplastic lesions and pancreatic cancer cells." (PMID 37270580, 2023).
adult T-cell leukemia (2 papers, 2020 to 2022). "In adult T-cell leukemia/lymphoma (ATL), HDAC8 expression was driven by an oncogenic cascade of FRA-2/JUND and SOX4 transcription factor, and— together with other two activated genes, GCKR and NAP1—was proven to affect ATL cell growth." (PMID 35887172, 2022). "A previous report has shown that FOSL2 is constitutively expressed in adult T-cell leukemia (ATL), up-regulates CCR4 expression, and promotes ATL cell growth, together with JunD proto-oncogene, AP-1 transcription factor subunit (JUND)." (PMID 33385611, 2020).